NOTCH1 (notch receptor 1)
Diseases named in the same sentence as NOTCH1 in open-access papers (continued):
Sharing a sentence is not in itself a finding about the gene and the disease.
triple-negative breast carcinoma (47 papers, 2011 to 2025). An invasive breast carcinoma which is negative for expression of estrogen receptor (ER), progesterone receptor (PR), and human epidermal growth factor receptor 2 (HER2). "Activating variants in the PEST region of NOTCH1 have been associated with aggressive phenotypes in human cancers, including triple-negative breast cancer (TNBC)." (PMID 35186194, 2022). "African American (AA)-triple negative breast cancer (TNBC) cells exhibit increased activation of Notch1, a key protein associated with poor survival." (PMID 34889737, 2021). "Recent clinical study in triple negative breast cancer has identified PEST domain mutation in Notch1, leading to the activation of Notch pathway." (PMID 26121683, 2015). "MB157 and MDA-MB-157 cell lines, both of which were derived from the same patient with triple-negative breast cancer, possess a NOTCH1 rearrangement associated with high levels of activated NOTCH1 protein and are also highly sensitive to Notch and pan-HDAC inhibitors." (PMID 38043798, 2024). "Notch1 has been implicated specifically in triple negative breast cancer EMT." (PMID 34295896, 2021). "For instance, ATRA exerts a significant anti-tumor action on TNBC (Triple Negative Breast Cancer) cells characterized by constitutive activation of the NOTCH1 (Neurogenic locus NOTCH Homolog protein 1) cell membrane receptor." (PMID 38360674, 2024). "Cordycepin suppressed the transcriptional activity of Gli, which in turn reduced the expression of Notch1, Notch3, Jagged1 and Hes1 in human triple-negative breast cancer cells (MDA-MB-231 cell line)." (PMID 39092224, 2024). "Celastrol and triptolide both reduced the expression of Notch1 and its downstream target proteins, hence regulating the renewal of stem cells in triple negative breast cancer." (PMID 39092224, 2024). "Genistein also inhibits tumor growth in pancreatic, colon, and triple-negative breast cancers by inhibiting NF-κB activity via the Notch1 pathway." (PMID 39092224, 2024). "Specifically inhibiting human Notch1 in triple negative breast cancer enhances the antitumor efficacy of chemotherapy and decelerates tumor growth by reducing cancer stem cells." (PMID 33413403, 2021). "GLI1 and Notch1 pathways are upregulated in African American (AA)-triple negative breast cancer (TNBC) in comparison to White American (WA)-TNBC." (PMID 34889737, 2021). "We observed an increase of Nanog only in MDA-MB-231 and SUM159PT triple-negative breast cancer cells and an increase of Notch1, Aldh1a1 and Aldh1a3 only in the SUM159PT cell line." (PMID 32610610, 2020). "Our previous study revealed that TRIB3 can interact with DDX5/BNIP/BCLAF1 in radioresistant MDA-MB-231 cells; thus, it is involved in the self-renewal and radioresistance of triple-negative breast cancer cells by regulating Notch1 activation." (PMID 33334065, 2020). "miR-9 has an inhibitory role in papillary thyroid cancer by targeting BRAF and reduces metastatic behavior in triple-negative breast cancer by targeting NOTCH1." (PMID 32258122, 2020). "Both MSI-1 and MSI-2 were well-expressed in triple-negative breast cancer samples and showed strong correlations with Notch pathway elements Notch-1 and Notch-2." (PMID 32245259, 2020). "For example, hsa-mir-5684-p3_1ss18CG targeting major vault protein (MVP), which was found to be regulated by Notch1 and contribute to overcome chemoresistance in triple-negative breast cancer cells." (PMID 32293320, 2020). "Both NF-κB and Notch-1 pathways are mainly expressed in triple negative breast cancer, the cancer subtype with the worst prognosis among all breast cancer subtypes." (PMID 26703550, 2015). "The inhibition of NF-κB activity by genistein can be mediated via Notch-1, a signaling pathway with an important regulatory role in triple negative breast cancers." (PMID 26703550, 2015).
triple-negative breast carcinoma (continued). "We have previously shown that Nicastrin regulates the EMT process and stem cell content in triple-negative breast cancers partially through Notch1/Notch4 activation." (PMID 24919951, 2014). "Most T-LLs and CLLs showed evidence of ongoing NOTCH1 activation, as did many peripheral T cell lymphomas and a small subset triple-negative breast cancers." (PMID 23825651, 2013). "Indeed, triple-negative breast cancer exhibits distinctive patterns of Notch expression, and EGFR and Ki-67 are positively associated with Notch1." (PMID 26121683, 2015). "Recently, a study by Speiser and collaborators showed increased Notch1 and Notch4 levels in tumor epithelial cells and vascular endothelial cells in triple-negative breast cancer samples, therefore highlighting the relevance of Notch4 expression in the vasculature." (PMID 23601498, 2013). "In the present study, we identified CD73 as a direct downstream target of Notch1, with CD73 expression promoting resistance to cisplatin in triple-negative breast cancer cells." (PMID 37391408, 2023). "It is found that miRNA-34a acts as a tumor suppressor miRNA through Neurogenic Locus Notch Homolog Protein 1 (NOTCH1) and CD44 signaling to induce apoptosis and suppress tumor proliferation, migration, and growth in Triple-Negative Breast Cancer (TNBC) cells." (PMID 37107631, 2023). "Celastrol can reduce the activation of Notch-1 and the expression of HES-1 and HEY-1 of the downstream target protein and inhibit the stem cells of triple-negative breast cancer, thereby reducing the possibility of distant metastasis." (PMID 36506508, 2022). "Inhibition of Notch and GLI1 enhances the effect of carboplatin in African American (AA)-triple negative breast cancer (TNBC); Notch1 and GLI1 are overexpressed in AA-TNBC tissues in comparison to TNBC tissues from White American (WA) women." (PMID 34889737, 2021). "PEA3 is a transcriptional activator of Notch-1 and Notch-4 and a repressor of Notch-2 in MDA-MB-231 cells, an example of triple-negative breast cancer cells." (PMID 21679465, 2011). "Notch1 and Sox2 have been shown to act in a negative feedback loop to suppress each other in triple-negative breast cancer, and Sox2+ tumours have enhanced CSC attributes compared to Notch1+ tumours." (PMID 40754577, 2025). "Recently, in an in vitro model of triple negative breast cancer, poly (lactic-co-glycolic acid) (PLGA) NPs loaded with miR-34a mimics and Notch1 antibodies are able to stop tumor growth by inhibiting Notch1 signaling and by miR-34a-mediated activation of tumor suppressive genes." (PMID 34527667, 2021). "The aim of this study was to investigate the influence of the Notch1 activity level on the pharmacological interaction between cisplatin (CDDP) and two histone deacetylase inhibitors (HDIs)—valproic acid (VPA) and vorinostat (SAHA) in the triple negative breast cancer (TNBC) cells." (PMID 31357442, 2019). "Due to the lack of untreated patients, the predictive impact of NOTCH1 overexpression cannot be formally assessed in HER2-positive and triple-negative breast cancer." (PMID 39153127, 2025).
bladder cancer (45 papers, 2012 to 2025). "Surprisingly, research has revealed that loss-of-function mutations in NOTCH pathway components and NOTCH1 gene copy losses occur in up to 60% of bladder cancers." (PMID 38602556, 2024). "Based on previous reports, mutations of ATM, NF1, and NOTCH1 in bladder cancer are found in approximately 15%, 10%, and 50% of cases, respectively." (PMID 37892022, 2023). "Activation of Notch signaling pathway caused by abnormally high expression of Notch1 is one of the molecular events in invasive bladder cancer." (PMID 35903544, 2022). "Our in vitro studies show DAC activation of immune-related (IL-6 and viral defense) and differentiation-associated (NOTCH1) transcripts and proteins in bladder cancer cell lines." (PMID 29242529, 2017). "Finally, the novel signaling molecules, including laminin, integrin α6β4, and Notch1, can serve as potential prognostic and diagnostic indicators of bladder cancer." (PMID 35585515, 2022). "In addition, the TCGA database analysis also revealed Notch 1 was associated with a poor prognosis of bladder cancer." (PMID 35585515, 2022). "lncRNA HCG18 can upregulate NOTCH1 by competitively binding to miR-34c-5p, thereby inhibiting bladder cancer." (PMID 40303288, 2025). "Overall, considerable research supports the function of Notch1 as a tumor suppressor in bladder cancer." (PMID 38797752, 2024). "This is supported by subsequent cancers that demonstrated the functional insufficiency of NOTCH1 and NOTCH2 mutations that were previously found in bladder cancers." (PMID 38602556, 2024). "The promoting effect of isoflurane on bladder cancer metastasis was suggested to occur through HIF-1α-β-catenin/Notch1 pathways." (PMID 37345096, 2023). "The most frequently mutated genes in bladder cancer samples in the present study were ATM, NF1, and NOTCH1." (PMID 37892022, 2023). "Silence of integrin α6 or β4 suppressed the upregulation of Notch1 in laminin/collagen cultured cancer cells, suggesting that laminin promoted Notch1 signals activation through integrin α6β4 in bladder cancer." (PMID 35585515, 2022). "For CC17, miR-455-5p has been shown to induce cisplatin resistance in bladder cancer cells by regulating Notch1." (PMID 36322407, 2022). "Accumulating reports have emphasized the regulatory roles of Notch1 in malignant cancers, such as tongue cancer, nasopharyngeal carcinoma, bladder cancer and so on." (PMID 35030977, 2022). "We demonstrated that laminin promoted Notch 1 signals activation through integrin α6β4, thereby facilitating bladder cancer cell proliferation and migration." (PMID 35585515, 2022). "Our study demonstrated that extracellular laminin can trigger tumor cell proliferation/migration through integrin α6β4/Notch1 signaling in bladder cancer." (PMID 35585515, 2022). "In bladder cancer, Notch1 has also been reported to serve as tumor suppressive and oncogenic roles to regulate cancer cell proliferation and migration." (PMID 35585515, 2022). "Studies have shown that neurogenic locus notch homolog protein 1 (Notch1) plays a part in accelerating bladder cancer and bladder TICs." (PMID 34904301, 2022). "In bladder cancer, Notch-1 regulates the proliferation and differentiation of cancer cells by inhibiting the expression of KLF4." (PMID 34367275, 2021). "Among these, NOTCH1, CCND1, CD44, MMP7, TGFR2, and FGFR3 are involved in bladder cancer signaling pathways or are associated with the development of bladder carcinoma." (PMID 33535616, 2021). "In bladder cancer, miR-34c-5p enhances proliferation and migration of bladder cancer cells through targeting of NOTCH1." (PMID 33800656, 2021). "In bladder cancer, miR-34c-5p enhances proliferation and migration of malignant cells through NOTCH1 targeting." (PMID 34205829, 2021). "The results suggested that variation, or molecular heterogeneity, of NOTCH1 expression within the microtumor can promote the invasiveness of heterogeneous bladder cancer." (PMID 34831307, 2021).
bladder cancer (continued). "Among the lncRNAs, although HCG18 had not been selected, it was found that lncRNA HCG18 suppressed the bladder cancer progression by cooperating with NOTCH1 and miR-34c-5p." (PMID 32196072, 2020). "m6A modification of Notch1 (Neurogenic Locus Notch Homolog Protein 1) decreases its RNA stability, leading to inhibition of bladder cancer and bladder tumor-initiating cells." (PMID 32765970, 2020). "miR-34a can downregulate the protein levels of HNF4γ and Notch1 in bladder cancer and endometrial cancer cells." (PMID 33221743, 2020). "For example: studies show that NOTCH1 is oncogenic and increases cell proliferation and invasive potential of bladder cancer cells in vitro." (PMID 29242529, 2017). "Our study further demonstrated that laminin could mediate bladder cancer development through a Notch1 dependent manner." (PMID 35585515, 2022). "Downregulation of NOTCH1 by hsa-mir-200c/mir-141 may also sensitize tumors to methotrexate thus suggesting potential chemotherapeutic options for bladder cancer subjects." (PMID 35845108, 2022). "Importantly, a poor overall survival of bladder cancer patients with high Notch1 expression was observed by utilizing TCGA database analysis." (PMID 35585515, 2022). "Additionally, Notch1 overexpression rescues emodin-induced cell growth suppression, indicating that emodin inhibits the proliferation of bladder cancer cells via the Notch1 pathway." (PMID 33996570, 2021). "Another case is the lncRNA HCG18, possessing the most gain interactions, which could cooperate with NOTCH1 to regulate the proliferation and migration of bladder cancer cells." (PMID 34222227, 2021). "Furthermore, NOTCH1, which sup-presses basal phenotypes and bladder cancer progression, negatively regulates the formation of a DLL4 expressing subpopulation that promotes collective cancer invasion." (PMID 34831307, 2021). "Moreover, it is reported that HCG18 suppresses cell PLF and MGT in bladder carcinoma via modulating miR‐34c‐5p/NOTCH1 axis." (PMID 32725768, 2020). "The essential role of Notch1 in Mettl14 function was confirmed in T24 bladder cancer cell line." (PMID 31760940, 2019). "Our work defined the oncogenic role of Notch1 in bladder cancer." (PMID 31760940, 2019). "For example, CHIR upregulates both β-catenin and Notch3 proteins in non-small lung cancer cell lines, although functional relevance of Notch3 in bladder cancer is unknown compared to Notch1 and Notch2." (PMID 29541396, 2018). "Recently, mutations in Notch1,2,3 have been described in head and neck cancers and alterations in the expression of DLL1 have been described in several tumors, including oral squamous cell carcinoma and urinary bladder cancer." (PMID 23056603, 2012). "Also, we found the activation of Notch 1 in bladder cancer is dependent on TRB3/JAG1 signaling." (PMID 35585515, 2022). "This led us to investigate whether NOTCH1 signaling is clinically important in bladder cancer." (PMID 29242529, 2017). "Therefore, we investigated whether DNA methylation regulates NOTCH1 expression or activation in bladder cancer cells." (PMID 29242529, 2017). "Importantly, epigenetic regulation of NOTCH1 expression leads to activation of downstream effectors that may possess tumor-suppressive properties in bladder cancer." (PMID 29242529, 2017). "In bladder cancer, METTL14 suppressed the development and progression of cancer cells by regulating Notch1." (PMID 39054337, 2024). "NOTCH1, NOTCH2 and NOTCH4 were significantly downregulated in bladder cancer samples compared with controls." (PMID 37728427, 2023). "In bladder cancer, NEDD4 exerts its oncogenic function by regulating phosphatase and tensin homolog (PTEN) and notch receptor 1 (NOTCH1) expression." (PMID 34458018, 2021). "Our study shows for the first time that DAC restores NOTCH1 expression and promotes IL-6 mediated CK5-differentiation in muscle-invasive bladder cancer cells." (PMID 29242529, 2017).
bladder cancer (continued). "In 2014, Greife and colleagues examined the canonical NOTCH1 signalling pathway and found it to be downregulated, along with its ligand DLL1, throughout all stages and histological grades of bladder cancer, with the lowest levels observed in high-stage tumours." (PMID 41008920, 2025). "Although influential studies by Rampias and Maraver reported NOTCH1 and NOTCH2 mutations in bladder cancer, NOTCH3 was not studied." (PMID 41008920, 2025). "They evaluated the activity of NOTCH1 and MAPK pathways in advanced stages (III and IV) of bladder cancer tissue samples from patients treated with radical cystectomy and assessed their relationship with clinical outcomes, such as cancer-specific survival and overall survival." (PMID 41008920, 2025). "In bladder cancer hepatic metastasis, isoflurane activated the HIF-1α-β-catenin/Notch1 pathways." (PMID 37345096, 2023). "Abnormal expression of Notch1, Hes1 and PTEN genes in invasive bladder cancer." (PMID 35903544, 2022). "In addition, the inhibition of HOTAIR has been demonstrated to regulate Notch1-mediated EMT pathways in bladder cancer and thereby promoting metastatic properties of bladder cancer." (PMID 36685879, 2022). "Since EMT promotes cancer cell migration and invasion, the suppression of miR-34a-Notch1 axis-induced EMT may be the regulatory mechanism of DNMT3B knockdown in suppressing the migration and invasion in bladder cancer." (PMID 33221743, 2020). "In this study, we show that non-cytotoxic nanomolar DAC concentrations modify the bladder cancer transcriptome to activate NOTCH1 at the mRNA and protein level, increase double-stranded RNA sensors and CK5-dependent differentiation." (PMID 29242529, 2017). "This suggests that while Notch 1 may not play a role in proliferation of bladder cancer cells, it has a key player in CSCs, resulting in aggressive tumor growth." (PMID 34059639, 2021). "Moreover, different Notch paralogs may have different actions in cancerous transformation; for example, it has been described that NOTCH1 and NOTCH3 have disparate roles from NOTCH2 in bladder cancer." (PMID 28915655, 2017).